MAPK8 (mitogen-activated protein kinase 8)
Diseases named in the same sentence as MAPK8 in open-access papers (continued):
Sharing a sentence is not in itself a finding about the gene and the disease.
lung carcinoma (153 papers, 2009 to 2025). "Through pathway enrichment analysis, we observed 14 pathways associated with lung cancer, with 12 linked to EGFR, 10 to HRAS, and 8 to MAPK8." (PMID 41155483, 2025). "MAPK8 is associated with the production and elimination of reactive oxygen species (ROS), while FAS mainly participates in cellular apoptosis in lung cancer." (PMID 30497474, 2018). "Among these, CAV1 and JNK (MAPK8) were identified as central hubs of the apoptosis-related interactome network in the cordycepin-treated lung cancer cells." (PMID 28099944, 2017). "Genes up-regulated in vascular smooth muscle cells by MAPK8, and genes up-regulated in the Kras2LA lung cancer mouse model, are enriched in the list of down-regulated genes." (PMID 24722050, 2014). "Although miR-214-3p’s exact role in LUAD is not fully understood, CircTADA2A can trap miR-214-3p and eukaryotic translation initiation factor 4A3 (EIF4A3) to boost mitogen-activated protein kinase 8 (MAPK8) levels, promoting invasion and migration in lung cancer cells." (PMID 40191724, 2025). "Moreover, we assessed the death risk of lung cancer patients using 4 target genes related to let-7a-5p, including BCL2L1, IGF1R, MAPK8, and FAS." (PMID 31508368, 2019). "Expression and alterations of BCL2L1, IGF1R, MAPK8, and FAS were investigated in lung cancer using TCGA database, and 4105 clinical samples provided by 13 studies were utilized in this study." (PMID 30497474, 2018). "High expression of BCL2L1 elevated lung cancer patients death risk [hazard ratio (HR) and 95% confidence intervals (CI) = 1.60(1.38–1.86)], but no similar correlations were found in IGF1R, MAPK8, and FAS." (PMID 31508368, 2019). "The expression of exosomal let-7a-5p was detected in pneumoconiosis, and all potential target genes related to exosomal let-7a-5p were predicted, among which four target genes related to lung cancer were selected for downstream analysis, including BCL2L1, IGF1R, MAPK8, and FAS." (PMID 30497474, 2018).
prostate carcinoma (146 papers, 2000 to 2026). A carcinoma that arises from epithelial cells of the prostate gland. "MAPK8/JNK1 inhibitors have been developed for cancer therapy and specifically for prostate cancer cells, as MAPK8/JNK1 inhibits autophagy and promotes survival and proliferation of cancer cells in an androgen-independent manner." (PMID 35317831, 2022). "Thus, MAPK8/JNK1 inhibition results in autophagy induction and subsequent decrease in prostate cancer proliferation." (PMID 35317831, 2022).
melanoma (139 papers, 2008 to 2026). A malignant, usually aggressive tumor composed of atypical, neoplastic melanocytes. "Inhibition of melanoma autophagy through targeting at ATG5, p62/SQSTM1 and BECN1 activates MAPK8/JNK-JUN/c-Jun signaling pathway in melanoma cells which up-regulates CCL5 cytokine in the TME and thus enhance NK function via activation of NK cell activator NKp46." (PMID 36003368, 2022). "The activation of the MAPK8 in melanoma could trigger the massive functional natural killer cells infiltration." (PMID 33922038, 2021).
ovarian carcinoma (116 papers, 2005 to 2025). A malignant neoplasm originating from the surface ovarian epithelium. "Another MAPK8 inhibitor, WBZ_4, has shown strong antitumor effects in ovarian cancer models both in vitro and in vivo." (PMID 40468448, 2025). "The MAPK8 gene encodes the stress-activated kinase JNK1, and its activated form is associated with shorter PFS in epithelial ovarian cancer." (PMID 37400764, 2023). "This suggests that WDR62 might mediate the JNK signaling pathway through interacting with MAPK8 and thus regulate the cell cycle to affect the progression of ovarian cancer, but further experimental verification is needed." (PMID 40369663, 2025). "Based on bioinformatic analysis, it was hypothesized that WDR62 might mediate the JNK signaling pathway by interacting with MAPK8, thus affecting ovarian cancer progression through cell cycle regulation." (PMID 40369663, 2025). "Importantly, studies have demonstrated that MAPK8 exhibits significant pro-cancer effects in ovarian cancer, with MAPK8 inhibition showing notable antitumor effects both in vivo and in vitro." (PMID 40369663, 2025). "Further analysis suggests that WDR62 may interact with MAPK8 to mediate the JNK signaling pathway, and thus regulating the cell cycle to impact ovarian cancer progression." (PMID 40369663, 2025). "This suggests that MAPK8 may play a critical role in ovarian cancer, further validating that WDR62 may interact with MAPK8 thereby promoting ovarian cancer progression." (PMID 40369663, 2025). "Interestingly, miR-141-3p upregulation and MAPK8 (JNK1) signaling downregulation have been reported in platinum-based chemotherapy in ovarian cancer cell lines." (PMID 33133155, 2020). "Additionally, interaction and correlation analyses suggest that WDR62 may affect ovarian cancer progression by interacting with MAPK8 (also known as JNK1) to mediate the JNK signaling pathway." (PMID 40369663, 2025). "Therefore, we hypothesize that WDR62 interacts with MAPK8, thereby regulating the cell cycle and promoting the development of ovarian cancer." (PMID 40369663, 2025). "Notably, MAPK8 showed the highest correlation with WDR62 in ovarian cancer (R = 0.4, p < 0.05)." (PMID 40369663, 2025). "Therefore, we speculated that WDR62 might interact with MAPK8 in ovarian cancer." (PMID 40369663, 2025). "WDR62 promotes ovarian cancer progression by regulating the cell cycle and may influence its development through interaction with MAPK8 to mediate the JNK signaling pathway." (PMID 40369663, 2025). "Combined with the previous discussion, MAPK8 is a key molecule in the JNK signaling pathway, and WDR62 may interact with MAPK8 to promote the progression of ovarian cancer." (PMID 40369663, 2025).
colorectal cancer (104 papers, 2009 to 2026). A primary or metastatic malignant neoplasm that affects the colon or rectum. "SOD2 contributes to the chemical resistance of colorectal cancer, and according to research, MAPK8 can promote the progression of colorectal cancer." (PMID 36299603, 2022). "The studies have indicated that increased MAPK8 plays a critical role in the development of colorectal cancer, and MAPK14 downregulation could effectively impede the poor behaviors of the clear cell renal cell carcinoma." (PMID 36438897, 2022). "Consistently, positive regulators of Akt signaling, such as Akt (Z-score = 1.626, p = 1.18E–06), IGF2 (Z-score = 2.025, p = 4.70E–10), TGFA (Z-score = 2.251, p = 1.96E–04), and MAPK8 (Z-score = 2.231, p = 4.01E–05), were activated in recurrent colorectal cancers." (PMID 33425893, 2020).
gastric cancer (94 papers, 2010 to 2026). A primary or metastatic malignant neoplasm involving the stomach. "In this study, ChIP-seq and HiChIP-seq experiments revealed mitogen-activated protein kinase 8 (MAP3K8) to be an SE-associated gene with chromosome interactions in Epstein–Barr virus-associated gastric carcinoma (EBVaGC) cells." (PMID 36768307, 2023). "For example, MAPK8 is oncogenic in the development of gastric cancer in mice induced by N-methyl-N-nitrosourea." (PMID 40369663, 2025).
glioma (93 papers, 2007 to 2025). A benign or malignant brain and spinal cord tumor that arises from glial cells (astrocytes, oligodendrocytes, ependymal cells). "Interventions such as the antioxidant NAC or the inhibition of MAPK8/JNK activity have been demonstrated to mitigate ROS-induced parthanatos in glioma cells, suggesting that MAPK8 activation contributes to parthanatos by enhancing intracellular ROS levels." (PMID 39090114, 2024). "The results showed that MLK3 mRNA in human gliomas was negatively related to MAPK8, MAPK9, and MAPK10." (PMID 33692940, 2020). "Consistently, the hyperphosphorylation of microtubule‐associated proteins (MAP2 and MAP1B) revealed the activation of CAMK2G, GSK3A, GSK3B, MAPK8, and MAP4K6, corresponding to the active MAPK signaling pathway in glioma." (PMID 39716938, 2025). "A long non-coding RNA LINC01564 promotes glioma cell resistance to TMZ by upregulating Nrf2 expression, which counteracts the effects of MAPK8 ablation on glioma cell apoptosis and ferroptosis to inhibit ferroptosis." (PMID 36937406, 2023).
cardiac hypertrophy (92 papers, 2010 to 2025). "Similarly, the down-regulation of the p38 47 or JNK (MAPK8) 48 catalytic subunits in transgenic mouse models followed by stress induced through aortic banding has been previously shown to induce cardiac hypertrophy leading to heart failure." (PMID 20127684, 2010).
glioblastoma (91 papers, 2013 to 2025). The most malignant astrocytic tumor (WHO grade IV). "Pik3ca also interacts with Lrp8, a gene related to the onset of neuropsychiatric diseases, such as schizophrenia, Mapk8, a gene associated with reduced apoptosis in glioblastoma cells, and Sorl1, which is decreased in AD brains by regulating Aβ accumulation." (PMID 36614117, 2022). "However, overexpression of MAPK8 is also reported to be associated with the MAPK signaling pathway activated in temozolomide-resistant glioblastoma cells." (PMID 38798352, 2024). "Activating the MAPK signaling pathway by MAPK8 in glioblastoma cells accelerates proliferation, inhibits apoptosis, and promotes resistance to TMZ63." (PMID 40739397, 2025). "MAPK8 is an important member of the serine/threonine protein kinase family, responsible for regulating the proliferation and apoptosis of glioblastoma cells." (PMID 34868262, 2021). "MAPK8 accelerates cell proliferation and inhibits the apoptosis of glioblastoma cells." (PMID 33537240, 2020).
pancreatic cancer (81 papers, 2005 to 2025). "Recent pathway-based research indicated that MAPK8 was associated with rectal cancer and pancreatic cancer." (PMID 23874846, 2013).
leukemia (76 papers, 2002 to 2025). A malignant (clonal) hematologic disorder, involving hematopoietic stem cells and characterized by the presence of primitive or atypical myeloid or lymphoid cells in the bone marrow and the blood. "JNK has been shown to play an important role in initiation/development of B-ALL, as Mapk8 deficiency delays the onset of leukemia." (PMID 32552902, 2020).
Hepatic steatosis (74 papers, 2009 to 2026). Steatosis is a term used to denote lipid accumulation within hepatocytes. "MAPK8-associated diseases include fatty liver disease and hepatitis C. The pathways related to MAPK8 include the ATM (serine/threonine kinase) pathway and the link between physicochemical characteristics and toxicity-related pathways." (PMID 34335821, 2021). "Diseases associated with MAPK8 include fatty liver disease and renal fibrosis and the GO annotations related to this gene include transferase activity, transferring phosphorus-containing groups, and protein tyrosine kinase activity." (PMID 32182911, 2020). "As determined using integrated bioinformatics analysis, the MAPK8/FoxO signaling pathway is important for the development of cancer and fatty liver." (PMID 32508033, 2020). "Thus, we predict that TAM induces fatty liver by interfering with the MAPK8/FoxO signaling pathway." (PMID 32508033, 2020).
osteosarcoma (72 papers, 2006 to 2026). A usually aggressive malignant bone-forming mesenchymal neoplasm, predominantly affecting adolescents and young adults. "DUSP1 gene silencing has been shown to increase the expression of MAPK7 and MAPK8 transcripts in osteosarcoma cells suggesting reciprocal actions between them." (PMID 31035605, 2019).
Alzheimer disease (67 papers, 2011 to 2026). A progressive, neurodegenerative disease characterized by loss of function and death of nerve cells in several areas of the brain leading to loss of cognitive function such as memory and language. "The orthologue of A0A251ULZ4 in humans is found to be MAPK8 type known to be involved Alzheimer’s disease." (PMID 35164374, 2022). "Interestingly, AKT1, MAPK8, BCL2L1, FOXO3, and CTNNB1 were not only significantly associated with pathogenic genes (APP, MAPT, and PSEN2) but also with longevity in Alzheimer’s Disease." (PMID 36620771, 2022).
ischemia (67 papers, 2009 to 2025). A hypoperfusion of the BLOOD through an organ or tissue caused by a PATHOLOGIC CONSTRICTION or obstruction of its BLOOD VESSELS, or an absence of BLOOD CIRCULATION. "There was a marked increase in Mapk10 RNA expression in peripheral nerves with ischemia without any change in other members of the JNK family (Mapk8 and Mapk9) that are expressed in neurons." (PMID 31530804, 2019).
viral infection (67 papers, 2005 to 2026). "The MAPK8 gene is also known as JNK and has been identified as being affected by viral infection." (PMID 36298658, 2022). "The results showed that SKIV2L2, JAK2, PIK3CB, and MAPK8 were related to virus infection." (PMID 36298658, 2022). "Among several kinases regulating the expression of DEGs expression in our analysis, genes involved in MAPK cascades (MAPK1, MAPK2, MAPK8, and MAP3K7) have roles in host response to viral infection." (PMID 33521069, 2020). "MAPK1, MAPK3, MAPK8 and MAPK14 can be activated by stimulating phosphorylation during changes in the internal environment, such as osmotic pressure changes, oxidative stress, inflammatory factors and viral infection." (PMID 35165507, 2022).
atherosclerosis (66 papers, 2010 to 2025). A disease characterized by the build-up of fatty material and calcium deposition in the arterial wall resulting in partial or complete occlusion of the arterial lumen. "A recent study reported that loss of Mapk8 (also known as Jnk1) protects macrophages from apoptosis in low-density lipoprotein receptor null mice, which accelerates early atherosclerosis." (PMID 33679879, 2021). "The downregulation of the expression of MAPK8 can provide therapeutic atherosclerosis effects by promoting endothelial cell proliferation, inhibiting apoptosis, and suppressing the inflammatory response." (PMID 39334763, 2024). "The molecular mechanism analysis revealed that the active components of WGP have a positive influence on the four potentially important therapeutic targets of aging, atherosclerosis, or fatigue (i.e., FOS, ESR1, MAPK8, and SP1)." (PMID 39334763, 2024). "FOS, ESR1, MAPK8, and SP1 are important targets for anti-aging, anti-atherosclerosis, and anti-fatigue." (PMID 39334763, 2024). "The top three core genes of WGP-atherosclerosis were FOS, ESR1, and MAPK8." (PMID 39334763, 2024). "The top three WGP ingredients (quercetin, EGCG, and kaempferol) could bind stably to the top four core genes of aging, atherosclerosis, and fatigue (FOS, ESR1, MAPK8, and SP1), except that EGCG could not dock successfully with SP1." (PMID 39334763, 2024).
type 2 diabetes (63 papers, 2008 to 2025). "A decrease in MAPK8 gene expression in type 2 diabetes pancreatic beta cells could be due to, on the one hand, a shift in insulin signaling and glucose transport into the cell and, on the other hand, a decrease in chaperone activation and protein folding." (PMID 37569434, 2023). "Like other MAPKs, MAPK8 may affect insulin signaling and, therefore, play a role in the pathophysiology of type 2 diabetes." (PMID 37569434, 2023).
cervical carcinoma (62 papers, 2001 to 2025). A carcinoma arising from either the exocervical squamous epithelium or the endocervical glandular epithelium. "Studies on this gene encoding MAPK8 suggest that this kinase plays a key role in T cell proliferation, apoptosis, and differentiation, and may be a crucial protein in cervical cancer radioresistance." (PMID 29922514, 2018). "In human bladder and cervical cancer, Sestrin2 expression enhanced the autophagy of cancer cells by modulating the Sestrin2-dependent MAPK8/JNK1/JUN mechanism." (PMID 39309448, 2024). "For instance, the increase of TRIB3 expression in HeLa cervical carcinoma cells resulted in the inhibition of MAPK14, MAPK3/1 and MAPK8 (JNK) activities via binding to MAPK kinase." (PMID 24834131, 2014).
Sepsis (52 papers, 2010 to 2026). Sepsis is defined as life-threatening organ dysfunction caused by a dysregulated host response to infection. "The AUROCs for diagnosing sepsis using MAPK8, PTEN, PPARG, and STAT3 were calculated as 0.808 (95% CI 0.586–1.000), 0.842 (95% CI 0.643–1.000), 0.883 (95% CI 0.713–1.000), and 0.85 (95% CI 0.652–1.000), respectively." (PMID 40070882, 2025). "Therefore, the roles of MAPK3 and MAPK8 in regulating ferroptosis, sepsis inflammatory injury mechanisms, and immune responses warrant further exploration." (PMID 40070882, 2025). "Through bioinformatics analysis, we identified five genes associated with ferroptosis—MAPK3, MAPK8, PPARG, PTEN, and STAT3—that may contribute to sepsis-related tissue damage." (PMID 40070882, 2025). "In conclusion, our study successfully identified MAPK3, MAPK8, PPARG, PTEN, and STAT3 as potential ferroptosis-related genes involved in the progression of sepsis." (PMID 40070882, 2025). "The AUROCs of MAPK3, MAPK8, PPARG, PTEN in the diagnosis of sepsis were 0.751, 0.611, 0.781, 0.618, and 0.857, respectively." (PMID 40070882, 2025). "The results indicated that 8 genes (MAPK14, MAPK8, TLR4, MAP3K5, CYBB, DUSP1, MAPK1 and ATM) might be closely related to the occurrence of sepsis." (PMID 36117534, 2022). "We speculated that GAPDH, MAPK8, PIK3CB, and MMP9 may play important roles in the ARDS-specific neutrophil phenotype distinct from sepsis." (PMID 31531373, 2019).
bladder cancer (50 papers, 2010 to 2025). "Moreover, ANLN can upregulate the expression of MAPK8/MAPK9, activate phosphorylated JNK, and enhance the proliferation, migration, and invasion of bladder cancer cells while inhibiting apoptosis." (PMID 41573677, 2025). "Isorhapontigenin treatment effectively increased Sestrin2 by allowing JUN to bind to the AP-1-binding region of the Sestrin2 promoter via MAPK8/JNK1, which subsequently enhanced autophagy by converting LC-3I to LC-3II and increased apoptosis in human bladder cancer cells." (PMID 39309448, 2024). "The MAPK8 ceRNAs in K11M14 can regulate the expression of MAPK8 by competing shared miRNAs, which might be potential biomarkers for bladder cancer." (PMID 29340088, 2017). "MAPK8 belongs to the stress-activated protein kinase MAPK family and, as the authors suggested, ISO treatment increased MAPK8–JUN phosphorylation in bladder cancer cells." (PMID 37284849, 2023). "In bladder cancer, RAB14 overexpression was correlated with advanced stage and poor prognosis and was shown to activate the MAPK1/MAPK8 signaling pathway to enhance cellular migration and invasion." (PMID 36471277, 2022). "After treatment of UMUC3 and T24T bladder cancer cells with ISO, sestrin 2 expression was elevated by activation of the MAPK8/JUN pathway, and activated sestrin 2 induced autophagy and inhibited the growth of bladder cancer cells." (PMID 34784907, 2021). "Moreover, Sestrin2 is known to be downregulated in bladder cancer, and when Sestrin2 is induced in response to mitogen-activated protein kinase 8 (MAPK8)-JUN)-dependent transcription, it suppresses bladder cancer growth." (PMID 32882793, 2020).